ENG (endoglin)
Diseases named in the same sentence as ENG in open-access papers (continued):
Sharing a sentence is not in itself a finding about the gene and the disease.
vascular disorder (25 papers, 2006 to 2025). A general term used to describe any disease affecting blood vessels]. "HHT is a vascular disorder of localized imbalanced angiogenesis caused by mutations in ALK1 or endoglin, which implies that ALK1 signalling regulates angiogenesis related genes." (PMID 16594992, 2006). "Interestingly, endoglin is expressed by vascular endothelium and by syncytiotrophoblasts and altered levels of soluble endoglin are linked to vascular disorders as pre-eclampsia." (PMID 33919576, 2021). "Soluble endoglin (sENG) is an important biomarker of several cardiometabolic and vascular disorders." (PMID 41168366, 2025). "Next, the current literature on (pre) clinical, endoglin-based, PET, MR, NIRF, and ultrasound imaging in tumors will be reviewed, followed by the role of endoglin in imaging of vascular disorders." (PMID 33946583, 2021). "Use of NGS-based gene panels including not only ENG, ACVRL1 and MADH4 but also RASA1 and EPHB4 genes, which are associated with the HHT-like syndrome accelerates the diagnosis of these hereditary vascular disorders." (PMID 33807613, 2021). "Mutations in the genes of endoglin or in the endothelial transmembrane receptor ALK1, a TGF-β type I receptor, cause the vascular disorder HHT (termed HHT-1 and HHT-2 accordingly)." (PMID 25080347, 2014). "Specifically, all four patients with structural vasculopathy subtype had a monogenic etiology (4/4, 100%): KRIT1 for CCM, RNF213 for MD, ENG for HHT, and PKD1 for PKD." (PMID 36580209, 2023). "HHT is a vascular disorder and the research of the last 20 years has shown that the TGF-ß/BMP receptors endoglin and ALK1 and Smad4, as an intracellular signal transducer protein, are involved in the different angiogenic processes." (PMID 23805858, 2013). "ENG mutations were identified in HHT and PAH over two decades ago; yet no curative therapies are available for these vascular disorders." (PMID 41476036, 2025). "This study found that SSc patients with and without elevated sPAP had much higher levels of serum endoglin compared with healthy controls, suggesting that endoglin may be a potential biomarker of vasculopathy that is not specific to the pulmonary vasculature." (PMID 21048994, 2010).
cardiovascular diseases (22 papers, 2010 to 2025). "Collectively, the data identify endoglin as a suitable target for intraoperative and diagnostic imaging of the neovasculature in tumors, whereas for cardiovascular diseases, the evidence remains scarce but promising." (PMID 33946583, 2021). "Since endoglin is mainly expressed in endothelial cells, circulating soluble endoglin levels have been investigated in association with cardiovascular diseases, as with soluble Flt-1." (PMID 29937525, 2018). "In conclusion, soluble endoglin has been implicated in the pathogenesis of renal and cardiovascular disease." (PMID 21886815, 2011). "Statin therapy may become another therapeutic strategy for controlling endoglin-associated pathologic cardiovascular disease in humans." (PMID 24392114, 2014). "Despite the important roles of ENG and sENG in different cardiovascular diseases, the molecular mechanisms of ENG function and its role in the pathogenesis of HHT, PAH and PE remain elusive." (PMID 41476036, 2025). "Endoglin is a membrane glycoprotein primarily expressed by the vascular endothelium and involved in cardiovascular diseases." (PMID 32316263, 2020). "Total RNA was purified from plasma, and three selected miRNAs (miRNA-10a, miRNA-214, and miRNA-370), related to the pathobiology of cardiovascular diseases and potentially targeting ENG or ALK1, were measured by quantitative polymerase chain reaction." (PMID 32899377, 2020). "Circulating levels of soluble endoglin have been shown to be higher in the serum of patients with cardiovascular diseases with a significant inflammatory component." (PMID 29145462, 2017). "Increased circulating levels of endoglin+ endothelial microparticles (EMPs) have been identified in several cardiovascular disorders, related to severity." (PMID 26786759, 2016). "Ultimately, while the optimal choice of tracer (antibody, Fab fragment, nanoparticle) and imaging system (PET, MRI, NIRF, ultrasound) requires additional research, it is clear that endoglin has potential as a target for visualization of cardiovascular diseases." (PMID 33946583, 2021). "ENG was also involved in “transforming growth factor beta binding” and “hypothesized pathways in pathogenesis of cardiovascular disease”." (PMID 34944885, 2021). "These encouraging results represent a turning point in the understanding of the role of soluble endoglin in the pathophysiology of various cardiovascular diseases, and, imply that soluble endoglin has an impact on the inflammatory state during inflammatory-related diseases." (PMID 29145462, 2017). "Soluble endoglin (sEng) is emerging as a new biomarker for several cardiovascular diseases." (PMID 29145462, 2017). "Our data thus suggest that an elevation in the baseline concentration of soluble endoglin with progressive CKD is unlikely to play a causative role in the progression of CKD or the association of CKD with cardiovascular disease." (PMID 21886815, 2011). "Elevations in soluble endoglin concentration are unlikely to contribute to the progression of CKD or the predisposition of individuals with CKD to develop cardiovascular disease." (PMID 21886815, 2011). "Our findings suggest that increases in the baseline levels of soluble endoglin in individuals with CKD are unlikely to contribute to the progression of CKD or to explain CKD-associated cardiovascular disease." (PMID 21886815, 2011). "Soluble endoglin might represent a novel and exciting biomarker in cardiovascular disorders." (PMID 33640001, 2021). "Although the levels of sENG have been suggested as a biomarker of cardiovascular disease progression and treatment, it is possible that changes in sENG levels are the consequences of the changes in the protein levels of cell-surface ENG which may also play a role in the disease pathogenesis." (PMID 31431534, 2019).
cardiovascular diseases (continued). "Because endoglin appears to play key roles in the pathogenesis of renal and cardiovascular pathology, we hypothesized that elevations in the concentration of circulating endoglin in CKD could contribute to the progression of CKD and underlie the association of CKD and cardiovascular disease." (PMID 21886815, 2011). "We therefore hypothesized that an increase in soluble endoglin concentration as GFR declines might contribute to the progression of CKD or play a mechanistic role in the association of CKD with increased risks of developing and dying from cardiovascular disease." (PMID 21886815, 2011). "Patients with previous cardiovascular disease had higher numbers of CD14+/endoglin+ cells than those without previous cardiovascular disease." (PMID 29304136, 2018). "Endoglin, an ancillary TGF-β receptor, is a key player in angiogenesis, nitric oxide coupling and heart development that plays an important regulatory role in both renal and cardiovascular disease." (PMID 21886815, 2011).
infection (21 papers, 2006 to 2025). The state of being infected such as from the introduction of a foreign agent such as serum, vaccine, antigenic substance or organism. "Lung and liver endothelial cells were treated with VEGF, TGF-β1 and BMP9 for 30 min at 6, 20 or 60 h after infection that corresponded to normal, half reduction and loss of endoglin expression." (PMID 34445652, 2021). "Endoglin most likely favors the pro-inflammatory M1 macrophage decision and Endoglin deficiency in macrophages renders an individual prone to infection." (PMID 33287465, 2020). "Endoglin deficiency in macrophages predisposed animals to spontaneous infections and led to delayed endotoxin-induced mortality." (PMID 27010826, 2016). "Endoglin deletion in MΦ predisposes animals to develop infections by opportunistic bacteria, where S. aureus is the most predominant pathogen identified." (PMID 27010826, 2016). "More recently, a myeloid-specific endoglin knockout model has been generated, which exhibits increased incidence of sporadic infections." (PMID 25114380, 2014). "Finally, a conditional knockout mouse approach of Endoglin in the myeloid lineage (Engfl/fl/LysMCre) revealed a reduced immune response in respective mice with spontaneous infections mostly Staphylococcus aureus." (PMID 33287465, 2020). "The results show a novel role for endoglin in mouse macrophages, which if analogous in human macrophages, may explain, at least in part, the increased infection rates seen in HHT patients." (PMID 27010826, 2016). "The low incidence of spontaneous infections in Engwt/flLysMCre mice may be due to a threshold effect where endoglin has to fall below a critical level in MΦ in order to show the infectious phenotype." (PMID 27010826, 2016). "Again, endoglin levels are raised following infection by a variety of organisms, with a particularly clear example that it is a marker of infection coming from the fact that there is raised endoglin only in infected vs. aseptic loosening in joints following arthroplasty." (PMID 27965958, 2016). "In our model, mice lacking endoglin on MΦ (Engfl/flLysMCre) were susceptible to develop infections by opportunistic bacteria after being set up in breeding pairs." (PMID 27010826, 2016). "These potential novel roles for endoglin may be important for understanding the resolution of inflammation and the higher incidence of infections in HHT patients." (PMID 25114380, 2014). "Therefore, mice with MΦ lacking endoglin show increased susceptibility to infection by opportunistic bacteria." (PMID 27010826, 2016). "Mice lacking endoglin expression in MΦ exhibit increased susceptibility to spontaneous infections, an impairment of phagocytic activity, and an aberrant leukocyte recruitment to the site of infection." (PMID 27010826, 2016). "Other marker genes that have been shown to be expressed in giant cells during late stage of infection include auxin resistant 1 (Aux1), auxin efflux carrier 4 (PIN4), endo-1,4-beta-glucanase (ENG), pectate lyase like (PLL), and Formin 2A." (PMID 41209832, 2025). "Due to the high frequency of infections seen in HHT, the role of endoglin in macrophages has been analyzed." (PMID 41039222, 2025). "Notably, endoglin silencing suppressed cell adhesion induced by infection, whereas ectopic expression of endoglin triggered cell adhesion to ECM and prevented infection-induced cell detachment." (PMID 41039222, 2025). "A low but significant increase in granzyme B (GrzB) release was measured 48 h after MOPV infection, whereas a nonsignificant increase of endoglin levels was observed at the same timepoint for both viruses." (PMID 35337059, 2022).
genetic disease (11 papers, 2013 to 2025). "HHT1 or Osler–Rendu–Weber syndrome 1 is a genetic disorder characterized by a deficiency in endoglin." (PMID 36735117, 2023). "Studies of ENG in both mice and human individuals have revealed a crucial role of the TGFβ signaling during angiogenesis and the resulting HHT1 genetic disease." (PMID 39247590, 2024).
retinopathy (8 papers, 2010 to 2024). "In support of this, it has been shown that increased expression of Endoglin results in retinal neovascularization and retinopathy in mice." (PMID 37386247, 2023). "Furthermore, elevated levels of soluble endoglin have been reported in the aqueous humor of different retinopathies, endoglin being a promising therapeutic target in these pathological conditions." (PMID 34445542, 2021). "We found a strong relation between Sol-endoglin plasma levels and retinopathy." (PMID 21171985, 2010). "It has been shown that endoglin promotes angiogenesis in cell- and animal-based models of retinal neovascularisation and treatment with anti-CD105 antibody inhibits neovascularisation in oxygen-induced retinopathy model." (PMID 33235244, 2020). "Blocking mTOR signalling can reverse shunts in mice lacking BMP9/10 and in Endoglin mutant zebrafish, like vascular malformations in mice with overactivated PI3 kinase signalling or in a model of oxygen induced retinopathy." (PMID 39656297, 2024).
infectious disease (3 papers, 2016 to 2022). A disorder directly resulting from the presence and activity of a microbial, viral, or parasitic agent in humans. "Overall, the altered immune activity of endoglin deficient macrophages could help to explain the higher rate of infectious diseases seen in HHT1 patients." (PMID 27010826, 2016). "Interestingly, this altered function of endoglin-deficient MΦ could help to explain the higher rate of infectious diseases seen in patients with HHT1, a vascular disease caused by heterozygous mutations in the endoglin gene." (PMID 31242676, 2019). "Another limitation of our study is the fact that confounding conditions, such as undiagnosed infectious diseases or unknown drug interaction, could potentially have affected plasma levels of endoglin." (PMID 34587660, 2022). "Furthermore, this impairment of the innate immune response seen when endoglin is absent from MΦ may help to explain the high frequency of infectious diseases observed in HHT patients." (PMID 27010826, 2016).
renal disease (3 papers, 2011 to 2022). "We then analyzed the interaction between the different kidney diseases and endoglin expression to be able to compare the angles of inclination." (PMID 36614087, 2022). "Since TGF-β plays central roles in renal fibrosis, previous animal studies focused on profibrotic effects of endoglin in kidney diseases." (PMID 29937525, 2018).
bacterial infection (2 papers, 2016 to 2025). "The interplay between endoglin and integrins has also been postulated to be involved in bacterial infections, more specifically in the shedding of infected epithelial cells, also called exfoliation, which acts as a natural defense to inhibit bacterial colonization." (PMID 41039222, 2025).
CNS tumors (2 papers, 2012 to 2023). "Endoglin (CD105) inhibition has been demonstrated to be of utility in advanced non-CNS tumors in several clinical trials." (PMID 37684373, 2023).
blood cancer (1 paper, 2023). "We have shown that while loss of cell surface ENG decreases BMP9 signaling in endothelial cells, knocking down ENG in blood cancer cells enhances BMP9 signaling." (PMID 37095146, 2023).
head and neck tumors (1 paper, 2023). "An increasing number of studies point to endoglin as a potential marker in various types of head and neck neoplasms." (PMID 36844233, 2023). "The expression of endoglin in various benign and malignant head and neck tumors, reported in different studies." (PMID 36844233, 2023). "However, even though TRC105, the anti-endoglin antibody was tested as a potential therapeutic agent in various solid tumors, there is a lack of similar studies in head and neck neoplasms." (PMID 36844233, 2023).
ENG also shares sentences with these, for which no sentence is quoted: pulmonary hypertension (12 papers); adenocarcinoma (8); osteoarthritis (8); ischemic stroke (7); non-small cell lung carcinoma (7); acute myocardial infarction (6); gastric tumors (5); brain tumor (4); congestive heart failure (4); connective tissue disease (4); pituitary adenomas (4); Alzheimer disease (3); autoimmune disease (3); colorectal tumors (3); Crohn disease (3); endometrioid carcinoma (3); hereditary hemorrhagic telangiectasia type 2 (3); infarction (3); infiltrative ductal carcinoma (3); Insulin resistance (3); laryngeal carcinoma (3); lipoma (3); meningioma (3); oral cancer (3); oral squamous cell carcinoma (3); Parkinson’s (3); periodontitis (3); peripheral artery disease (3); psoriasis (3); adenoid cystic carcinoma (2).
A further 188 diseases each share a sentence with ENG in 2 papers or fewer.